VCAN-AS1 (VCAN antisense RNA 1)
Gene: Long non-coding RNA gene on chromosome 5 (83,531,352 to 83,581,320, reverse strand). Ensembl gene ENSG00000249835.
Diseases named in the same sentence as VCAN-AS1 in open-access papers:
VCAN-AS1 is named in the same sentence as 3 diseases in open-access papers, as found by Europe PMC text mining. Sharing a sentence is not in itself a finding about the gene and the disease. The quoted sentences say what the papers report.
gastric cancer (1 paper, 2023). A primary or metastatic malignant neoplasm involving the stomach. "A survival study identified 15 genes associated with gastric cancer prognosis, including VCAN-AS1, SERPINE1, AL139002.1, LINC00326, AC018781.1, C15orf54, hsa-miR-145." (PMID 37696973, 2023).
VCAN-AS1 also shares sentences with these, for which no sentence is quoted: adenoma (1 paper); cancer (1).